PRM1 (protamine 1)
Description:
Protamines substitute for histones in the chromatin of sperm during the haploid phase of spermatogenesis. They compact sperm DNA into a highly condensed, stable and inactive complex.
Synonyms: CT94.1; P1
Tractability: No criterion of Open Targets' tractability assessment is met for any kind of drug.
Gene: Protein-coding gene on chromosome 16 (11,280,841 to 11,281,330, reverse strand). Ensembl gene ENSG00000175646.
Subcellular location: Nucleus; Chromosome
Subcellular location (Human Protein Atlas): Cytosol; Nucleoplasm
Pathways (Reactome):
Developmental Biology: Replacement of protamines by nucleosomes in the male pronucleus
Gene Ontology:
Molecular function: protein binding; DNA binding
Biological process: chromosome organization; spermatogenesis; sperm DNA condensation
Cellular component: cytosol; nucleoplasm; chromosome; nucleosome; nucleus
Genetic constraint (gnomAD): Loss-of-function variants: 5 observed, 6.11 expected, observed/expected ratio (o/e) 0.82, 90% interval 0.43 to 1.64. That is too few expected variants to judge how well the gene tolerates losing a copy. Missense variants: 82 observed, 73.8 expected, observed/expected ratio (o/e) 1.11, 90% interval 0.93 to 1.34. Synonymous variants: 28 observed, 22.85 expected, observed/expected ratio (o/e) 1.23, 90% interval 0.91 to 1.67.
Homologues: Orthologues: rabbit PRM1 (67% identical).
Diseases named in the same sentence as PRM1 in open-access papers:
PRM1 is named in the same sentence as 38 diseases in open-access papers, as found by Europe PMC text mining. Sharing a sentence is not in itself a finding about the gene and the disease. The quoted sentences say what the papers report.
infertile (32 papers, 2010 to 2025). "Loss of both PRM1 alleles leads to infertility whereas loss of one PRM1 allele results in severe reduction of sperm motility and male subfertility." (PMID 37766963, 2023). "In contrast, ablation of βcatenin in germ cells using Axin2cre and Protamine 1-cre leads to premature germ cell loss, reduced sperm count and infertility." (PMID 27992363, 2016). "Since the ratio between PRM1 and PRM2 is constant in mature sperm (in mice ~60% PRM2), and alterations of this ratio are associated with sperm defects and infertility, we next tested if male mice harboring the Prm2Δc allele display alterations of the PRM1/PRM2 ratio." (PMID 35763544, 2022). "However, unlike in mice and humans, where another variant of PRM, PRM2, must have a similar ratio as PRM1, and a ratio that deviates at the protein and mRNA levels, will impact infertility." (PMID 35324839, 2022). "A potential explanation for the association between PRM1 -190C > A polymorphism and infertility is that the region encompassing this polymorphism resulted in clear DNase I footprint protection in vitro, spanning an adjacent serum response element and the serum extended protection region." (PMID 26472740, 2015). "Therefore, it is reasonable to hypothesize that the -190C > A polymorphism leads to changes in expression of the PRM1 gene, resulting in abnormal sperm morphology and PRM1/2 content as well as infertility." (PMID 26472740, 2015). "Both protamine 1 and protamine 2 showed altered phosphorylation and methylation patterns, with overall protamine 1 phosphorylation significantly higher in infertile men than in fertile men." (PMID 40649876, 2025). "Sperm from infertile men show altered PRM1/PRM2 ratio or undetectable PRM2 in mature sperm, with a PRM1/PRM2 >1 ratio and embryos derived from sperm deficient in PRM2 had their development affected." (PMID 41393904, 2025). "Insufficient protamine incorporation is further indicative of increased retention of histones, as sperm from infertile men exhibited increased histone H2B and reduced Prm1:Prm2." (PMID 39600339, 2024). "Insufficient PRM-1 and PRM-2 concentrations have been implicated in subfertile or severe infertile condition." (PMID 32960520, 2021). "In line with the mentioned study, a survey showed thatPRM2 down-regulation occurred much more than PRM1 inthe sperm of infertile men." (PMID 34155862, 2021). "Without the function of KDM3A in round spermatids, excessive methylation would lead to the transcription suppression of TNP1/PRM1 genes and the occurrence of infertility in animal models." (PMID 33349804, 2020). "In humans, small changes in the ratio of PRM1 to PRM2 can also lead to infertility." (PMID 38928079, 2024). "There is a significant overexpression of miR27a in infertile men with nonobstructive azoospermia, which target several genes, including H3K9 demethylase that regulates transcriptional suppression of Tnp1/Prm1, resulting in infertility in animal models and humans." (PMID 36899892, 2023). "Alterations of the species-specific ratio between PRM1 and PRM2 are associated with infertility." (PMID 35763544, 2022). "The results showed PRM1 rs2301365 and PRM2 rs1646022 polymorphisms were associated with an elevated risk of male infertility and PRM2 rs2070923 polymorphism had a protective role in infertile men." (PMID 33057064, 2020). "PRM1 rs2301365 and PRM2 rs1646022 polymorphisms were associated with an elevated risk of male infertility and PRM2 rs2070923 polymorphism had a protective role in infertile men." (PMID 33057064, 2020). "Additionally, the infertility of Prm2+/Δc strongly suggests a dominant effect of the deletion, possibly due to an aberrant interaction with another key protein such as transition proteins, PRM1 or H2A.L.2." (PMID 35763544, 2022). "The infertility of Prm1+/− mice might be caused not by critical sperm DNA damage but by reduced sperm motility resulting from an abnormal tail structure and disturbed energy metabolism." (PMID 27250771, 2016).
infertile (continued). "Without the function of KDM3A in round spermatids, excessive methylation would lead to transcriptional suppression of transition protein 1 (TNP1) and protamine 1 (PRM1) genes and the occurrence of infertility in animal models." (PMID 39876905, 2024). "In a study on bulls, the RNA levels of PRM1 were reduced in low-fertility animals, and in humans, PRM1/PRM2 sperm ratios differed between fertile and infertile men." (PMID 33292187, 2020). "Consequently, the lack of TNP1 and PRM1 genes expression leads to the loss of the required condensation of chromosomes for proper packing in the sperm head, and it is considered as one of the causes of infertility in NOA men." (PMID 33349804, 2020). "Onthe basis of the studies which showed high PRM1/PRM2 ratios, it has been supposed that a reductionin PRM2 expressions was responsible for aberrantPRM1/PRM2 ratios in infertile males." (PMID 26644857, 2015). "Lewiset al. observed that in sperm of infertile men,PRM2 downregulation occurred much more frequentlythan PRM1 deregulation, because PRM2expression was more sensitive to the variation ofregulatory controlling mechanisms than those forPRM1." (PMID 26644857, 2015). "In non-human models, haploinsufficiency of Prm1 and Prm2 in mice results in infertility due to reduced motility, chromatin integrity, and morphology." (PMID 39600339, 2024). "Also, the same study reported alterations in the PRM1:PRM2 ratio and higher rates of DNA fragmentation in men with infertility/subfertility antecedents, which decreased the success of in vitro reproduction techniques, such as intracytoplasmic sperm injection (ICSI) and in vitro fertilization (IVF)." (PMID 36381269, 2022). "Similarly, the post-meiotic spermatid marker PRM1 (which indicates chromosome condensation) was evidently expressed after SCCM induction at day 19 of culture (p = 0.02), as shown in, its slight expression was also observed in the RA group on infertile donor treated AD-MSCs 19 days after culture." (PMID 37122886, 2023).
male infertility (21 papers, 2012 to 2024). The inability of the male to effect fertilization of an ovum after a specified period of unprotected intercourse. "Many genes have been investigated in the context of male infertility; monogenic variants are correlated with disruptive spermatogenesis, resulting in reduced sperm counts and male infertility, for instance PRM1, NR5A1, MTHFR, and MTSR." (PMID 38540436, 2024). "Although a distinct pathway has not been found yet, the reduced transcription of postmeiotic genes, including Tnp1, Tnp2, Prm1 and Prm2, in Brwd1-defective testes has been suggested to cause male infertility." (PMID 34473250, 2021). "With regard to PRM1 rs2301365 polymorphism, the C allele and CA genotype in the Caucasian ethnicity were associated with the elevated risk of male infertility (OR 1.96; 95% CI 1.29, 2.97; P = 0.002 and OR 1.79; 95% CI 1.13, 2.83; P = 0.01, respectively)." (PMID 33057064, 2020). "As in our meta-analysis, there was an elevated risk of male infertility for PRM1 rs2301365 polymorphism only in Caucasians and for PRM2 rs1646022 polymorphism only in Asians." (PMID 33057064, 2020). "For PRM1 rs2301365 polymorphism, the C allele and CA genotype in the studies with PCR-based method were associated with the elevated risk of male infertility (OR 1.96; 95% CI 1.29, 2.97; P = 0.002 and OR 1.79; 95% CI 1.13, 2.83; P = 0.01, respectively)." (PMID 33057064, 2020). "Based on the results, C allele and CA genotype of PRM1 rs2301365 polymorphism were associated with the elevated risk of male infertility." (PMID 33057064, 2020). "A meta-analysis evaluated the potential association between male infertility and 6 common SNPs of PRM1 & PRM2 including rs35576928, rs737008, rs35262993, rs2301365, rs1646022, rs2070923." (PMID 30123866, 2018). "Iguchi et al19 have reported a correlation of PRM1 c.197G>T polymorphism and male infertility." (PMID 36197138, 2022). "It was also suggested that PRM1 c.-190C>A polymorphism may lead to male infertility due to abnormal sperm morphology." (PMID 36197138, 2022). "The variations in the regulatory areas of PRM1 gene, may interfere with some critical factors related to PRM1 gene expression, hence cause male infertility." (PMID 36405559, 2022). "This is also the case in humans, since impaired protamine 1/2 ratio and accumulation of pre‐PRM2 are associated with male infertility." (PMID 37099396, 2023). "In this study, we tried to find the association of some SNPs of PYGO2, PRM1, PRM2, and DAZL genes with male infertility." (PMID 36197138, 2022). "This study was performed to investigate the correlation of some single nucleotide polymorphisms of PYGO2, DAZL, PRM1, and PRM2 genes with male infertility in idiopathic cases among the Iranian population." (PMID 36197138, 2022). "Several genetic mutations, including PRM1, AURKC, SPATA16, PICK1, DPY19L2, SEPT12, and SEPT14, result in male infertility and are caused by sperm DNA damage in a clinical context." (PMID 36295569, 2022). "The histone-to-protamine transition is a tightly controlled process, as premature expression of protamine 1 or disruption of protamine genes results in male infertility in mice." (PMID 34803926, 2021). "The association between PRM1 and PRM2 polymorphisms and the risk of male infertility was evaluated using specific search terms in the Web of Science, Cochrane Library, PubMed, and Scopus databases without language restriction until January 28, 2020." (PMID 33057064, 2020). "The results of meta-regression showed that publication year was a cofounding factor involved in the association between PRM1 rs737008, PRM1 rs2301365, and PRM2 rs1646022 polymorphisms and susceptibility to male infertility." (PMID 33057064, 2020). "The aim of the present meta-analysis was to evaluate the association between PRM1 (rs737008 and rs2301365) and PRM2 (rs1646022 and rs2070923) polymorphisms and susceptibility to male infertility." (PMID 33057064, 2020).
male infertility (continued). "It has been shown that PRM1 and PRM2 variants are related to male infertility in both humans and animals." (PMID 33057064, 2020). "Our data showed that rs737008 and rs2301365 in PRM1, and rs1646022 in PRM2, were significantly associated with male infertility and that gene–gene interaction played a role in male infertility." (PMID 28977892, 2017). "Previous studies have shown that rs737008 and rs2301365 in PRM1, and rs1646022 in PRM2, were significantly associated with male infertility." (PMID 28977892, 2017). "Our study showed that rs737008 and rs2301365 in PRM1, and rs1646022 in PRM2, were significantly associated with male infertility and that gene–gene interactions played a role in male infertility." (PMID 28977892, 2017). "We observed differential expression of a number of transcripts, such as PRM1, SPATA18, TNP1, EIF4G2, CANX, RANBP9, TCP11, which have previously been associated with male infertility." (PMID 25973848, 2015). "For example, PRM1 is a potential biomarker for spermatogenesis and the diagnosis of male infertility." (PMID 24312499, 2013). "This study has evaluated frequency of six previously reported variations in protamine genes cluster consisted of reported mutations in PRM1, PRM2 and TNP2 and their relationship to male infertility in Iranian population." (PMID 25246894, 2012). "Also, variants of PRM1 and PRM2 have been shownto be associated with male infertility and abnormal spermmorphology." (PMID 30644249, 2019). "Thus far, only a few studies have analyzed the correlation between PRM1/2 and TNP1 polymorphisms and particular phenotypes of male infertility." (PMID 28977892, 2017). "According to the literature, spermatogenesisbased disorders in male infertility have a significant relationship with the expression level of some RNA molecules(like DAZ and PRM1/PRM2 ratio) in semen and testicular tissue." (PMID 34155862, 2021). "A number of reports have verifieddifferent variations in PRM1 and PRM2 sequences(NM_002761.2 and NM_002762.3) in humans with variousassociations with male infertility." (PMID 30644249, 2019). "Recent investigations represented different variations in PRM1, PRM2 and TNP2 gene sequences in human with various relationships to male infertility." (PMID 25246894, 2012). "Additionally, an alteration in the ratios between protamines 1 and 2 (PRM1/PRM2) and aberrations in the histone-to-protamine ratios correlate with male infertility." (PMID 32847119, 2020). "However, we found that the PRM1 and PRM2 haplotypes GCTGC, TCGCA and TCGCC exhibited significant protective effects against male infertility compared to fertile men, while TCGGA, GCTCC and TCGGC represented significant risk factors for spermatogenesis." (PMID 28977892, 2017). "A variety of studiesreported a relationship between abnormal PRM1/PRM2 ratios and male infertility." (PMID 26644857, 2015). "In conclusion, we found that the PRM1 and PRM2 haplotypes GCTGC, TCGCA and TCGCC exhibited significant protective effects against male infertility as compared to fertile men, except for TCGGA, GCTCC and TCGGC which could represent a significant increased risk of spermatogenesis." (PMID 28977892, 2017). "Consequently, downstream genes which are controlled by KDM3A such as PRM1 and TNP1 are not expressed and all these together drive to male infertility in NOA men." (PMID 33349804, 2020).
Azoospermia (8 papers, 2012 to 2025). Absence of any measurable level of sperm,whereby spermatozoa cannot be observed even after centrifugation of the semen pellet. "The results of that research showed that the expression of all the studied genes including KDM3A, TNP1, and PRM1 in all histological groups of azoospermia men with the tissue pattern of SCOC suggested a significant difference in the expression of hypospermatogenesis." (PMID 33349804, 2020). "The expression levels of germ-cell-specific mRNAs such as protamine 1 (PRM1), protamine 2 (PRM2), deleted in azoospermia (DAZ), and A-kinase anchoring protein 4 (AKAP4) have also been associated with SRR outcomes, with detectable levels linked to higher SRR rates in some studies." (PMID 39767586, 2024). "TXNDC2, along with protamine 1 and 2 (PRM1 and PRM2), was significantly decreased in patients with different patterns of NOA compared to OA patients, suggesting that TXNDC2, PRM1, and PRM2 have a robust power to predict sperm retrieval and are correlated with phenotypes of severe azoospermia." (PMID 37174638, 2023). "TXNDC2 (effect size = − 4.25, FDR = 1.44E−15), PRM1 (effect size = − 5.37, FDR = 1.99E−10), PRM2 (effect size = − 5.16, FDR = 3.60E−10), and TNP1 (effect size = − 7.05, FDR = 6.48E−16) were all downregulated in the idiopathic azoospermia dataset." (PMID 34158577, 2021). "The association of PRM1/2 with male azoospermia is well-documented, but the relationship between TXNDC2 deficiency and the azoospermia phenotype, sperm retrieval, and pathology has not been elucidated." (PMID 34158577, 2021). "The expression ratio of histone demethylase KDM3A to protamine-1 mRNA has been proposed as a reliable marker for successful TESE in men with both obstructive and non-obstructive azoospermia." (PMID 40901096, 2025).
asthenozoospermia (3 papers, 2018 to 2024). "To analyse the function of ODFs in asthenozoospermia, we excised exons 6 and 7 of the Odf2 gene by prm1‐cre to disrupt the formation of ODFs in Odf2flox/flox mice." (PMID 29168316, 2018). "Among these nine highly prevalent polymorphism areas, the allele frequencies of three SNPs in asthenozoospermia men including 373C>A (r s2070923) and 298G>C (rs1646022) in PRM2 and 139C>A (rs737008) in PRM1 were insignificantly higher than the control group." (PMID 30123866, 2018). "The human PRM1 and PRM2 gene sequences were screened in search of potential mutations in highly prevalent polymorphism regions in asthenozoospermia versus normozoospermia." (PMID 30123866, 2018). "In humans, patients with low sperm motility (asthenozoospermia) have imbalanced histone–protamine 1/2 ratio, modified levels of cytoskeletal proteins and we detected retained Septin 12 isoforms (Mw 40 and 41 kDa) in the sperm membrane, chromatin-bound and tubulin/mitochondria protein fractions." (PMID 39524225, 2024). "Therefore, this research evaluated the polymorphism of PRM1 and PRM2 in men, diagnosed with asthenozoospermia." (PMID 30123866, 2018).
colon cancer (2 papers, 2021 to 2022). "Protamine 1 (PRM1) was found to affect colon cancer proliferation, invasion, migration, diagnosis, and prognosis." (PMID 33521125, 2021).
Obesity (2 papers, 2012 to 2024). Accumulation of substantial excess body fat. "Furthermore, obesity led to a decrease in ubiquitinated H2A (ubH2A) and reduced levels of histone H3 acetylation K18 (H3AcK18) and histone H4 acetylation K5, K8, K12, and K16 (H4tetraAck), which disrupted protamine 1 (Prm1) deposition in testis tissue." (PMID 38668519, 2024).
teratozoospermia (2 papers, 2015 to 2019). "A polymorphism in the PRM1 promoter (190C.A) is known to increase PRM1 to PRM2 ratio.The aim of our study was to examine the association of SNPsin PRM1 and PRM2 with idiopathic teratozoospermia." (PMID 30644249, 2019). "Tuttelmann and colleagues proposed that 5 SNPs (rs35262993, rs35576928, rs737008, rs1646022 and rs2070923) of PRM1 and PRM2 are associated with mild oligozoospermia (n = 77) or teratozoospermia (n = 88) in a Caucasian population." (PMID 26472740, 2015). "However, there wereno significant differences in SNPs of PRM1 and PRM2between the two groups for c.230A>C, the frequencyof the CA genotype was significantly higher in infertilemen with teratozoospermia." (PMID 30644249, 2019).
varicocele (2 papers, 2024 to 2025). A condition characterized by the dilated tortuous veins of the spermatic cord with a marked left-sided predominance. "Similarly, elevated protamine-1/protamine-2 ratios have also been observed in varicoceles, which is thought to have downstream consequences impacting chromatin packaging, ultimately affecting the expression of key genes." (PMID 38392299, 2024).
adenoma (1 paper, 2023). A neoplasm arising from the epithelium. "Additionally, by detection of three paired tissues from patients who were diagnosed simultaneously with CRC and colorectal adenoma, the expression level of PRM1 was very low in normal tissues, but it was upregulated in adenoma and the highest in cancer." (PMID 36593375, 2023).